LINC01094 (long independently transcribed non-coding RNA 1094)
Diseases named in the same sentence as LINC01094 in open-access papers (continued):
Sharing a sentence is not in itself a finding about the gene and the disease.
cancer (17 papers, 2020 to 2026). A tumor composed of atypical neoplastic, often pleomorphic cells that invade other tissues. "LINC01094 is a recently identified lncRNA found to be dys-regulated in an assortment of cancer tissues and control multiple biological processes via competing endogenous RNA (ceRNA) mechanisms." (PMID 41623379, 2026). "Numerous recently published reports have shown that LINC01094 exerts critical functions during the regulation of malignant cell growth, migrating ability, and invasiveness, thereby controlling cancer cell growth and metastasis." (PMID 41623379, 2026). "In this review, multiple cancer biology functions of LINC01094 documented in published literature are summarized, aiming to inspire innovations in the management of human malignancies under laboratory and clinical settings." (PMID 41623379, 2026). "LINC01094 is a cancer-promoting molecule correlated with many classical signaling pathways, such as the Wnt/β-catenin pathway and PI3K/AKT pathway." (PMID 39719596, 2024). "In brief, this series of experiments indicated that the cancer-promoting effects of LINC01094 in GC depend greatly on the LINC01094-RBMS2/HDAC1-CDKN1A axis." (PMID 39719596, 2024). "According to studies, LINC01094 has an essential function in the advancement and invasion of several cancer types." (PMID 36824662, 2023). "LINC01094 was found to play a role as a cancer-promoting factor in many tumors." (PMID 36935487, 2023). "Moreover, LINC01094 expression seemed increased as the cancer stage grew, though with p-value slightly higher than 0.05." (PMID 36052279, 2022). "Long intergenic non-coding RNA 01094 (LINC01094) is probably a novel regulator in cancer biology." (PMID 33069244, 2020). "Given that lncRNAs in the cytoplasm largely function as a competing endogenous RNA (ceRNA) in cancers, we wondered whether LINC01094 was an endogenous sponge of certain miRNAs." (PMID 32595418, 2020). "Hence, our study found an oncogenic lncRNA, LINC01094, which could be a promising target for cancer treatment and diagnosis." (PMID 39719596, 2024). "Therefore, LINC01094 can function as an oncogenic factor that may accelerate cancer progression across numerous cancer types." (PMID 36824662, 2023). "These also suggested that LINC01094 might involve in the cancer progression of CRC." (PMID 35287563, 2022). "This research revealed the upregulation of LINC01094 in CRC, which predicts poor overall survival and cancer progression." (PMID 35287563, 2022). "Then, according to the LncATLAS database, the expression of LINC01094 was higher in the cytoplasm, while FISH confirmed the up-regulated expression of LINC01084 in the cytoplasm of cancer cells." (PMID 33173535, 2020). "However, in cancer biology, the role of LINC01094 has not been fully elucidated." (PMID 33069244, 2020).
LINC01094 also shares sentences with these, for which no sentence is quoted: kidney cancer (2 papers); Kawasaki disease (1); liver cancer (1); mental disorder (1); nervous system diseases (1); Obesity (1); schizophrenia (1); systemic vasculitis (1).